CD52 (CD52 molecule)
Diseases named in the same sentence as CD52 in open-access papers (continued):
Sharing a sentence is not in itself a finding about the gene and the disease.
tumor (continued). "Based on the results of enrichment analysis and tic analysis, the immunomodulatory effect of CD52 in the tumor environment was speculated." (PMID 33240323, 2020). "In this study, we calculated the proportion of tumor-infiltrating immune cells (TICs) and the proportion of immune and matrix components of BC samples from The Cancer Genome Atlas (TCGA) database and determined a useful predictive biomarker CD52." (PMID 33240323, 2020). "Saporin immunotoxins have been well described and successful at targeting VLC Anti-murine CD52-saporin was administered to tumor bearing mice twice-weekly for three weeks and then animals were sacrificed 24 hours after the last administration of the immunotoxin." (PMID 19545375, 2009). "CD52, a glycoprotein highly expressed on lymphocytes and dendritic cells, may facilitate immune cell interactions within the tumor microenvironment (TME) or modulate immune synapse formation during antigen presentation, potentially influencing the efficiency of ICD-induced immune responses in UCEC." (PMID 40777132, 2025). "However, the patient was resistant to all treatments, and the tumor cells lost CD52 expression." (PMID 39513061, 2024). "Therefore, an anti-tumor antibody targeting CD52, such as alemtuzumab, is a potential therapeutic alternative for AML with FLT3-ITD, given that this antibody targets and kills leukemic cells by a mechanism that is different from that of the FLT3 kinase inhibitors." (PMID 34035227, 2021). "As the HRD score rises, the signal crosstalk between macrophage-related APOB-TREM2 and CD52-SIGLEC10 is concomitantly augmented, which is related to tumor immune evasion." (PMID 40830526, 2025). "Genes with reported anti-tumor functions, including SCGB1D2 (Secretoglobin Family 1D Member 2, lipophilin B), FKBP5, CD52, DLK1, GALNT9, GNG2, GDNF, and TMEM35A, were significantly upregulated after CUDC-907 + MPA treatment and validated by RT-PCR." (PMID 41262902, 2025). "Among the three subgroups of TAMs, these cells had higher scores for tumor activation (MHC-II and Cd52) and phagocytic function (Apoe and Lgals5), indicating that these TAMs still had certain antigen presentation capabilities." (PMID 39867913, 2024). "In analyzing B cells in the tumor microenvironment, B cells were separated into two clusters: one termed as follicular B cell, with high expressions of MS4A1, CD79B, CD52, and another termed as plasma cell, with high expressions of IGHG1, IGHG4 and MZB1." (PMID 38443340, 2024). "In the GEPIA database, it was demonstrated that tumor tissues had higher levels of ID3 and CD52 expression than normal tissues." (PMID 39256364, 2024). "The surface antigen CD52 was expressed in all included primary MCL cells and the CD52 level on the tumor cells was higher compared to healthy control B cells (H1, H2)." (PMID 36587029, 2022). "Beyond CLL, CD52 expression has been described in AML, different subtypes of mature T/NK neoplasms, B-ALL, and some cases of T-ALL." (PMID 33081391, 2020). "It includes antibodies directed against tumor cells belonging to the hematopoietic lineage, lymphocytes (CD20, CD52, CD38, etc.), and myeloid cells (CD30, CD33, etc.)." (PMID 28855903, 2017). "We also found that liver-derived CD52− NK cells exhibited 4-fold greater cytotoxicity toward K562 tumor cells and produced 20-fold more IFN-γ than liver-derived CD52+ NK cells when activated with IL-2." (PMID 27560943, 2016). "Treatment with anti-CD52 could induce CD68+ M1-like macrophage expression, promote tumor regression, and inhibit TGF-β1 signaling and epithelial-mesenchymal transition (EMT)." (PMID 40830526, 2025). "It found that CD52 and ID3 were broadly dispersed throughout the four tissue samples, with a relatively low level of sparse distribution in the normal tissue region and a relatively high level of sparse distribution in the tumor region." (PMID 39256364, 2024).
tumor (continued). "Therefore, new targeted therapies have been developed targeting surface molecules expressed on the surface of tumor cells, such as CCR4, HDACs, CD30, and CD25, CD52, specific for MF and SS." (PMID 37259456, 2023). "In addition, we investigated the efficacy of treatment with ibrutinib and CD52 mAb combined with active complement on viability and proliferation of MCL cell lines and primary tumor cells from ten MCL patients." (PMID 36587029, 2022). "Moreover, we found that alemtuzumab, an anti-CD52 antibody, induced stronger ADCC in K562–FLT3ITD/WT cells compared with that in K562–FLT3WT/WT cells and dramatically suppressed tumor growth by K562–FLT3ITD/WT cells in mouse xenograft experiments." (PMID 34035227, 2021). "Or with the anti-CD52 antibody alemtuzumab, both neutrophils and NK cells were shown to be capable of effectively exerting antibody-dependent cellular cytotoxicity (ADCC) on CD52-expressing tumor cells." (PMID 31205619, 2019). "The results of additional immunohistochemical studies (BCL2, MYC, Ki67) showed no impact on CD52 expression status, and tumor morphology (blastoid vs. DLBCL vs. DLBCL/BL) was similarly non-predictive." (PMID 30020951, 2018). "While CD31 mRNA was readily detected, no CD52 mRNA expression was detected in CD45(-)/VE-Cadherin+/CD146+ tumor endothelial cells (TECs)." (PMID 19545375, 2009). "To assess whether cytotoxicity of the IgG1-Campath-RGE and IgG1-11B8-AGK antibody combination is restricted to cells co-expressing CD52 and CD20, we analyzed the CDC activity of individual and mixed antibody components on six tumor B cell lines with variable CD52 and CD20 expression levels." (PMID 35879362, 2022). "CD52 protein was not expressed on CD45(-)/VE-Cadherin+ TECs or tumor cells." (PMID 19545375, 2009). "For tumor targeting applications, it could be beneficial to selectively permit ADCC activity for a tumor-specific antibody component (for example, CD20), when used in combination with a component that targets a more broadly expressed antigen (for example, CD52)." (PMID 35879362, 2022). "However, a number of anti-tumor antibodies target molecules expressed by tumor cells belonging to the hematopoietic lineage and, hence, also target their normal cell counterparts, notably lymphocytes (anti-CD20, -CD52, -CD38, SLAMF7, etc.)and myeloid cells (anti-CD30, -CD33, etc.)." (PMID 28855903, 2017). "While CCL5, CD52, DSTN and IL7R still exhibited a trend of high expression in tumour samples, but no significant discrepancy existed." (PMID 39098994, 2024). "CD52 is also the target of the monoclonal antibody alemtuzumab that has shown low anti-tumor activity in DLBCL patients based on a series of 11 relapsed or refractory cases, not characterized for CD52 expression." (PMID 32679859, 2020). "Altogether, these data indicate that SPN and MUC1 modulate tumor cell sensitivity to CD20xCD3 bsAb independent of CD20 expression, while increased expression of CD52 directly affects CD20 cell surface levels." (PMID 31882897, 2019).
cancer (23 papers, 2017 to 2026). A tumor composed of atypical neoplastic, often pleomorphic cells that invade other tissues. "For instance, Alemtuzumab, a CD52 targeting DMT, has a history in cancer treatment, and its use in MS has been linked to various malignancies." (PMID 39480835, 2024). "The expression of Cd52, Snap29, Mcoln1 and Nek6 genes, known to promote tumorigenesis in different cancer types, was up-regulated in peritoneal TCL1-Tg CLL cells." (PMID 38469292, 2024). "For instance, the CD52 gene (higher number of copies in the cancer prone group), a membrane glycoprotein expressed on the surface of mature lymphocytes, monocytes and dendritic cells, was one of the most significant hits of our analysis (p-value = 0.007)." (PMID 35741808, 2022). "Considering the importance of glycolysis in cancer, whether CD52 can regulate aerobic glycolysis in NSCLC cells has attracted our attention." (PMID 38817869, 2024). "We investigated whether the expression of ID3 and CD52 was related to cancer features using the UALCAN database." (PMID 39256364, 2024). "CD52 is an important functional regulator involved in the development of human cancer." (PMID 38817869, 2024). "For example, “don’t eat me” signal expression was either no change or mildly increased in Met1 cells but significantly increased in Met2 cells such as Cd274 (PD-L1), Cd52, and Tbxas1, indicating that these genes may play a significant role in immune evasion of metastatic cancer cells." (PMID 40458726, 2025). "Apart from molecular targets expressed in cancer cells of the three types of programs, CD52, CDK6, HDAC2, and PIGF were specifically expressed in inflammatory or EMT meta programs, indicating that drugs against these targets may respond in specific cancer cell subpopulations." (PMID 38944814, 2024). "Similar with CD3D and CD52, CD79A and CD37 can not only help us monitor specific T–B interactions, which is one of the major parts of the anti-cancer immune response, but can also provide us a new biomarker to evaluate the alteration of cancer microenvironment during tumorigenesis." (PMID 34575089, 2021). "Genes related to B and T cell maturation (e.g. CD37, CD79B, JCHAIN, IGLL1, VPREB3, CD52), ribosomal protein genes (RPS-*, RPL-*) and cancer/stress genes (e.g. PRAME, ARHGDIB, FOS, JUN) were within the most significantly deregulated genes between clusters in those samples." (PMID 32415257, 2020). "The function of CD52 is not well characterized, but it is thought to regulate immune responses and might play a role in cancer development." (PMID 36982699, 2023).
infection (11 papers, 2016 to 2025). The state of being infected such as from the introduction of a foreign agent such as serum, vaccine, antigenic substance or organism. "Solid organ transplantation, tumor necrosis factor-alpha inhibitors, and anti-CD52 agents have also been reported to increase the risk of clinical infection." (PMID 40801539, 2025). "Therefore, NCRs and NKG2D expressing CD52- NK cells can prevent microbial infection after cytokine activation, which is likely caused by inflammation or infection." (PMID 27560943, 2016). "Because CD52 regulates immune cells and the anti-CD52 antibody alemtuzumab reduces immunosuppression after transplantation, we hypothesized that increased CD52 serum levels might be linked to a higher incidence of infection after transplantation." (PMID 39281063, 2022). "Among the signals from macrophages to LZ GC B cells and memory B cells, the Lgals9-Ighm/Cd45 signaling showed a greater enhancement by PCV2 infection, while those signals that were originally stronger in the control group, such as Ptprc-Cd22, Cd52-Siglecg, and App-Cd74, were weaker." (PMID 41011514, 2025). "The upregulation of CD52 in CD4+ T cells in AD impairs antigen-specific T cell responses and thus potentially contributes to immunoparesis in AD, which leads to an increase in the risk of infection and mortality." (PMID 39276679, 2024). "In addition, patients who developed culture-positive infections had high CD52 MFI in CD4+ T cells than patients who were culture-negative, the CD52 MFI in CD4+ T cells was also correlated with serum C-reaction protein (CRP)." (PMID 39276679, 2024).
hematological malignancies (5 papers, 2020 to 2025). "Most monoclonal antibodies used in hematologic malignancies, such as rituximab (anti-CD20), alemtuzumab (anti-CD52), and daratumumab (anti-CD38), are not commonly associated with direct ocular toxicities." (PMID 41568391, 2025). "Moreover, the concept of sTRAIL fusion may also be applicable to antibodies targeting other important antigens in hematological malignancies such as CD20 and CD38 for which TRAIL fusion constructs were already described or further novel targets such as CD52 and CD79." (PMID 34203833, 2021).
CD52 also shares sentences with these, for which no sentence is quoted: rheumatoid arthritis (4 papers); acute myeloid leukemia (3); colon carcinoma (2); cryptococcosis (2); liver cancer (2); Opportunistic infection (2); systemic sclerosis (2); triple-negative breast carcinoma (2); adenovirus infection (1); adrenal carcinoma (1); adrenal cortical carcinoma (1); allergic asthma (1); autoimmune thrombocytopenia (1); B cell lymphopenia (1); B-cell neoplasm (1); breast invasive carcinoma (1); breast tumors (1); carotid atherosclerosis (1); central nervous system autoimmune disease (1); cerebral cavernous malformation (1); colitis (1); colorectal carcinoma (1); diffuse large B-cell lymphoma (1); encephalitis (1); endothelial dysfunction (1); esophageal squamous cell carcinoma (1); glioblastoma (1); glioma (1); Graves disease (1); gynecological tumors (1).
A further 31 diseases each share a sentence with CD52 in 1 paper.